MAOA (monoamine oxidase A)
Diseases named in the same sentence as MAOA in open-access papers (continued):
Sharing a sentence is not in itself a finding about the gene and the disease.
Alzheimer disease (24 papers, 2007 to 2025). A progressive, neurodegenerative disease characterized by loss of function and death of nerve cells in several areas of the brain leading to loss of cognitive function such as memory and language. "In Alzheimer’s disease, the activation of MAOA is directly correlated with altered concentrations of biochemical neurotransmitters in the brain." (PMID 40183081, 2025). "Monoamine oxidase-A (MAO-A) and MAO-B have both been implicated in the pathology of Alzheimer disease (AD)." (PMID 29997470, 2018). "Increased monoamine oxidase-A (MAO-A) activity in Alzheimer’s disease (AD) may be detrimental to the point of neurodegeneration." (PMID 37445985, 2023). "The RT extract reduces juglone-induced oxidative stress in worms and increases the lifespan and prevents paralysis of C. elegans CL4176, a model of Alzheimer’s disease; the extract is also able to inhibit enzymes such as acetylcholinesterase, monoamine oxidase A and tyrosinase in vitro." (PMID 34069854, 2021). "Alzheimer’s disease (AD) has been correlated to a reduced expression of the GirK2, GirK3, GirK4, KCNQ2, and KCNQ3 subunits and genes encoding for the antioxidants SOD, 8-oxoguanine DNA glycosylase (OGG1), and monoamine oxidase A (MAO-A) in rats." (PMID 32825356, 2020). "The use of biomarkers alone, be they preclinical biomarkers of Alzheimer’s disease or the MAOA allele, are not sufficient to fully predict future behavior." (PMID 31221862, 2019). "Moreover, the literature points out that berberine has inhibitory effects on four key enzymes related to the pathogenesis of Alzheimer s disease: monoamine oxidase B (MAO-B), acetylcholinesterase, monoamine oxidase A (MAO-A), and butyrylcholinesterase." (PMID 35668943, 2022).
Obesity (24 papers, 2009 to 2026). Accumulation of substantial excess body fat. "Polymorphisms in MAOA were found to be associated with obesity, a key factor contributing to the incidence of T2D." (PMID 33900023, 2021). "Here the authors report that male mice lacking the allograft inflammatory factor-1 protein are resistant to diet-induced obesity, in association with higher adipose norepinephrine levels and lower expression of the norepinephrine catabolic enzyme monoamine oxidase A." (PMID 36596796, 2023). "In these cells, MAOA's norepinephrine clearance activity has been linked to obesity." (PMID 31921150, 2019). "The dopamine levels influence the risk of obesity and MAOA and MOAB may be implicated in human obesity." (PMID 23241142, 2012). "Elevated AIF-1 levels correlate with inflammatory adipocytes and obesity, while reduced AIF-1 promotes weight loss through regulation of monoamine oxidase A and decreased leptin/resistin production." (PMID 41694567, 2026). "In eWAT, the increasing activity of the NLRP3 inflammasome leads to increases in MAOA oxidation, thereby dampening lipolysis and promoting obesity." (PMID 35046893, 2021). "Our research showed that ES suppresses MAOA in obesity, which decreased the degradation of NE." (PMID 35046893, 2021). "The extract was investigated as a neuroprotective inhibitor of central nervous system (CNS) enzymes such as monoamine oxidase A, tyrosinase, acetylcholinesterase, and as a natural enzyme inhibitor of α-glucosidase and lipase involved in some metabolic disorders such as obesity or type 2 diabetes." (PMID 32668697, 2020). "Low activity genotypes at both the MAOA and MAOB loci – showed a relative risk for obesity of 5.01." (PMID 30967134, 2019). "An association was observed between MAOA and obesity among white and Hispanic American subjects, but not among African–American subjects." (PMID 23554917, 2013). "Moreover, obesity in pregnant patients increases the odds of antenatal and postpartum depression through a complex genetic crosstalk between polymorphisms of serotonin (HTR2A), catecholamine (COMT and MAOA), HPA-axis (CRHR1), and oestrogen receptor genes." (PMID 41375608, 2025). "We link this phenotype to higher adipose NE levels that stem from decreased monoamine oxidase A (MAOA) expression and NE clearance by AIF1-deficient macrophages, and find through reciprocal bone marrow transplantation that donor Aif1-/- vs WT genotype confers the obesity phenotype in mice." (PMID 36596796, 2023). "The potential relevance of AIF1-dependent catecholamine catabolism to human obesity is supported by the positive correlation of AIF1 with MAOA and ALDH1L2 transcript levels in adipose tissues from participants with weight excess or obesity." (PMID 36596796, 2023). "For example, in obesity, SAMs in brown adipose tissue induce expression of solute carrier family 6 member 2 (SLC6A2) and monoamine oxidase A(MAOA)." (PMID 37020587, 2023). "Additionally, NAC suppressed the expression of key obesity-related proteins, including fatty acid binding protein 4 (FABP4), monoamine oxidase A (MAOA), heat shock protein 70 (HSP70), aminoacylase-1 (ACY-1), and transketolase (TKT) in 3T3-L1 cells." (PMID 41149623, 2025). "In addition, we provide evidence linking these findings to human obesity, in that AIF1 expression correlates positively with MAOA and ALDH1L2 levels in adipose tissues from individuals with weight excess or obesity." (PMID 36596796, 2023). "Interestingly, human sequence variants near the AIF1 locus associate with obesity and diabetes; in adipose samples from participants with obesity, we observe direct correlation of AIF1 and MAOA transcript levels." (PMID 36596796, 2023). "One study investigating MAOA and COMT genotypes in obese subjects compared to controls found no significant relation between the MAOA genotype and obesity." (PMID 37893019, 2023).
schizophrenia (24 papers, 2005 to 2025). A major psychotic disorder characterized by abnormalities in the perception or expression of reality. "Two hundred and forty-one subjects with schizophrenia and three hundred and seventy age and sex-matched healthy controls were genotyped for MAOA promoter uVNTR, 5-HTTLPR, and STin2 polymorphisms." (PMID 35079035, 2022). "The MAOA gene, also called the "warrior" or "violence" gene, was identified as a candidate susceptibility gene for schizophrenia and aggressive behavior, although the risk polymorphism has not been confirmed." (PMID 21978760, 2011). "Multiple neuropsychiatric conditions, such as schizophrenia (SHZ) and mood disorders, are associated with the dysfunction of metabolizing enzymes, including MAOA." (PMID 40149678, 2025). "Here, we aimed to investigate the association of three variable number tandem repeats (VNTR) functional polymorphisms in MAOA and SLC6A4 with schizophrenia in the Iranian population." (PMID 35079035, 2022). "We conclude that, whereas some mRNA changes are consistent with increased dopamine action (decreased DAT mRNA), others suggest reduced dopamine action (increased MAOA mRNA) in the midbrain in schizophrenia." (PMID 28094812, 2017). "Despite an existing theoretical rationale, there is a lack of studies assessing the effects of bupropion, reboxetine, SNRIs, and reversible inhibitors of monoamine oxidase A on cognitive function in schizophrenia." (PMID 25991654, 2015). "Nevertheless, other analyses found preliminary results in support of a sex-specific effect of MAOA with respect to schizophrenia diagnosis or select symptomatic aspects of the disorder." (PMID 24639636, 2014). "We analyzed uVNTR and rs1137070, polymorphisms from MAOA and rs1799836 of MAOB genes to perform single SNP case-control association study in a sample of 344 schizophrenia patients and 124 control subjects." (PMID 23738213, 2012). "The role of MAO genes in the susceptibility to schizophrenia requires further research; therefore, we analyzed MAOA and MAOB gene polymorphisms to perform single SNP association study in Mexican patients with schizophrenia." (PMID 23738213, 2012). "Here, we investigated the association of two representative functional polymorphisms, rs6323 of MAOA and rs1799836 of MAOB, with the development of schizophrenia in Han Chinese." (PMID 21978760, 2011). "Two functional single nucleotide polymorphisms (SNPs), rs6323 of MAOA and rs1799836 of MAOB, were selected for association analysis in 537 unrelated schizophrenia patients and 536 healthy controls." (PMID 21978760, 2011). "Polymorphisms of isoforms MAOA and MAOB have been implicated in the etiology of mental disorders such as schizophrenia." (PMID 21978760, 2011). "Here, we investigated the association of MAOA and MAOB polymorphisms with schizophrenia in a Han Chinese population." (PMID 21978760, 2011). "It is possible that functional variants in the MAOA and MAOB genes could predispose to antipsychotic-induced weight gain in patients with schizophrenia." (PMID 30967134, 2019). "MAOA mRNA was significantly increased by 45% in the substantia nigra in schizophrenia cases compared with controls (F=6.34, df=56, P=0.015), but no diagnostic changes were found in the levels of MAOB mRNA (F=0.81, df=53, P=0.372) or COMT mRNA (U=462, z=0.89, P=0.371)." (PMID 28094812, 2017). "If there is an increase in dopamine in the synaptic cleft in people with schizophrenia, we suggest that it is possible that the increase in MAOA mRNA may reflect a compensatory response to balance extracellular dopamine levels." (PMID 28094812, 2017). "Our preliminary findings could suggest that severity of affective flattening may be associated by modifier variants of MAOA and MAOB genes in female Mexican patients with schizophrenia." (PMID 23738213, 2012).
schizophrenia (continued). "In conclusion, our preliminary findings could indicate that the severity of negative symptoms might be associated by modifier variants of MAOA and MAOB genes in Mexican patients with schizophrenia, in particular, with affective flattening dimension." (PMID 23738213, 2012). "However, it was reported a high frequency of a particular MAOA haplotype in males with schizophrenia compared with a control group." (PMID 23738213, 2012). "Although both MAOA and MAOB genes have been suggested as genetic factors in the pathogenesis of schizophrenia, our findings only support the association of MAOB polymorphism with susceptibility to schizophrenia in Han Chinese." (PMID 21978760, 2011). "While the interaction between COMT Val158Met and MAOA uVNTR may be linked to schizotypy, this association has not been found to correlate with the development of schizophrenia in Indian and English populations." (PMID 39595853, 2024). "Biological pathways have been proposed and pursued, centering on the schizophrenia-linked candidate neurotransmitter dopamine; in rodents, infection with T. gondii leads to aberrant dopamine signaling and reduced expression of genes within the dopamine pathway, such as DRD1, DRD5 and MAOA." (PMID 26886853, 2016). "In addition to the evidence on schizophrenia, several findings have documented that genetic variations of MAOA may play a central role in neuropsychiatric disorders in a sex-dependent fashion." (PMID 24639636, 2014). "Midbrain monoamine oxidase A (MAOA) mRNA was increased, whereas MAOB and catechol-O-methyl transferase mRNAs were unchanged in schizophrenia." (PMID 28094812, 2017). "The distribution of MAOA and MAOB genotypes for schizophrenia and control groups were in Hardy-Weinberg equilibrium (P > 0.05)." (PMID 23738213, 2012).
breast carcinoma (23 papers, 2010 to 2025). "Moreover, Kaplan–Meier survival analysis demonstrated that high expression of MAOA is associated with improved overall survival in patients with various cancer types including breast cancer, kidney renal clear cell carcinoma, lung adenocarcinoma and bladder carcinoma." (PMID 36627132, 2023). "For example, it has been shown that norepinephrine and dopamine (substrates of MAOA) induced chemotaxis in breast cancer cells." (PMID 32273550, 2020). "Further studies supported that upregulated MAOA promoted angiogenesis in breast cancer 28 and contributed to the transition from epithelial to mesenchymal in lung cancer." (PMID 32931665, 2020). "In breast cancer cells, activation of IL-6/IL-6R signalling suppressed MAOA expression in hypoxic environment." (PMID 32273550, 2020). "MAOA was also proved to be correlated with the worse prognosis of HER‐2 subtype breast cancer." (PMID 32931665, 2020). "In this study, using TCGA data, HSD17B7, ACADL, ME1, MAOA, and TDO2 were identified as the top five DEGs related to FA metabolism in breast cancer tissues." (PMID 36936412, 2023). "This study is aimed at evaluating the effect of different monoamine oxidase A inhibitors (MAO-AIs) on the proliferation and progression of breast cancer cell lines." (PMID 37841082, 2023). "Moreover, previous studies have shown that the downregulation of MAOA may be associated with EBV-associated nasopharyngeal carcinoma, esophageal cancer, breast cancer, lymph node status (N0) of gastric cancer, cholangiocarcinoma, hepatocellular carcinoma, pheochromocytoma, and colon cancer." (PMID 34209963, 2021). "In an experimental study, the action of the monoamine oxidase-A (MAO-A) inhibitor clorgyline was evaluated in the epithelial ER-positive MCF-7 and the post-EMT (mesenchymal) ER-negative MDA-MB-231 human breast cancer cell lines." (PMID 29099748, 2017). "Similarly, for early breast cancer, the best three k-gene discriminators are {GPR109B, PCOLCE2, PCSK5}, {PCSK5+COL10A1, FERMT2+SPINT2, MAOA+IGJ}, {COL1A1+PCSK5+TF, GPX3+COL1A1+SPINT2, GPX3+FAP+TMEM97}, and {RRM2+COL1A1+GPR109B+IGJ, RRM2+COL1A1+GPR109B+IGJ, RRM2+COL1A1+GPR109B+SPINT2}, respectively." (PMID 21060876, 2010). "In short, antagonists of tryptophan hydroxylase 1 (TPH1), monoamine oxidase A (MAO-A), SERT and each of 5 of the 17 5-HTRs inhibited tumorsphere formation by each of six human breast tumor cell lines independent of the breast cancer subtype that they model." (PMID 32758183, 2020).
anxiety disorder (20 papers, 2015 to 2025). A category of psychiatric disorders which are characterized by anxious feelings or fear often accompanied by physical symptoms associated with anxiety. "Anxiety disorders have previously been linked to differential methylation of specific genes (MAOA, CRHR1, OXTR), and functional magnetic resonance imaging has revealed that the temporal and prefrontal regions of the brain respond differently in patients with anxiety disorders." (PMID 36846567, 2023). "During post-translational modification, the promoter/exon/intron region DNA methylation in the MAOA gene can produce anxiety disorders." (PMID 39410900, 2025). "These actions were shown to modulate crucial target proteins, including SLC6A4, COMT, and MAOA, thereby exhibiting a significant therapeutic impact on anxiety disorders." (PMID 38684743, 2024). "Research has demonstrated that both MAOA gene polymorphism and methylation contribute to the efficacy of CBT/iCBT in the treatment of anxiety disorders." (PMID 37497400, 2023). "Future studies should aim to elucidate the role of MAOA gene polymorphism and methylation in the efficacy of CBT/iCBT for various anxiety disorder subtypes." (PMID 37497400, 2023). "Current diagnoses varied by genotype: proportionately more MAOA-SL carriers, than SS or LL, presented anxiety disorders." (PMID 29600412, 2018). "Proportionately, more of the MAOA-SL carriers, than SS or LL, presented, at a trend, lifetime diagnoses of anxiety disorders." (PMID 29600412, 2018).
neuroblastoma (17 papers, 2012 to 2025). Neuroblastoma (NB) is the most common solid, extracranial childhood tumor. "We investigated the molecular mechanisms underlying MAOA expression in the human neuroblastoma cell line SH‐SY5Y which is both female and heterozygous for the uVNTR." (PMID 29667298, 2019). "However, the first functional study that reported the differential expression and activity of MAOA based on alleles (with different numbers of repeats) was through luciferase reporter gene fusions and the transfection experiments in cell lines of human neuroblastoma and placental choriocarcinoma." (PMID 40149678, 2025). "Overexpression of mice α-synuclein or the A53T mutant in mice neuroblastoma cells lines increases sp1 expression which, through the binding with the promoter, enhances MAOA expression." (PMID 36768321, 2023). "A previous study indicated that androgen can activate MAOA expression by AR-regulated Sp1 binding to MAOA promoter in human neuroblastoma and glioblastoma cells." (PMID 29066975, 2017). "It has been shown, for example, that the Y-encoded SRY (sex-determining region Y) transcription factor modulates MAOA (monoamine oxidase A) activity in human male neuroblastoma cells." (PMID 26475699, 2015). "We used the human neuroblastoma cell line SH‐SY5Y to address MAOA expression." (PMID 29667298, 2019). "In a human neuroblastoma cell line with transfected cDNA of the estrogen receptor (SK-ER3), estrogen receptor activation by a physiological concentration of 17β-estradiol was correlated with a marked decrease in MAOA activity." (PMID 22619623, 2012). "In primary human neuron culture and neuroblastoma cells expressing miR-142, decreased monoamine oxidase A (MAO-A) expression was observed compared to controls not expressing miR-142, which is one of the causes of neurotransmitter imbalance and neuronal dysfunction related to HAND." (PMID 34685718, 2021).